DICER1 (dicer 1, ribonuclease III)
Diseases named in the same sentence as DICER1 in open-access papers (continued):
Sharing a sentence is not in itself a finding about the gene and the disease.
thyroid tumor (continued). "RT-qPCR analysis revealed an upregulation of Bim in RET/PTC3 Dicer1(+/+) thyroid tumors compared to the WT thyroids from 2-month-old mice." (PMID 41002430, 2025). "Then, we quantified the loss of exon 24 in Dicer1 mRNA in RET/PTC3 Dicer1(−/−) and RET/PTC3 Dicer1(+/−) thyroid tumors compared to RET/PTC3 Dicer1(+/+) mice tumors." (PMID 41002430, 2025). "On the other hand, our RET/PTC3 Dicer1(−/−) thyroid tumors showed markedly decreased expression of Dicer1 exon 24 mRNA levels." (PMID 41002430, 2025). "This “DICER1-related pediatric thyroid neoplasm with follicular and morular growth” expands the spectrum of DICER1-associated thyroid lesions." (PMID 40892116, 2025). "Mutations in micro-RNA (miRNA) regulators DICER1 and DGCR8 have recently been uncovered, revealing a potential novel mechanism driving thyroid tumor development." (PMID 38252873, 2024). "Even when malignant, DICER1-mut tumors are associated with less invasive disease and generally have an excellent prognosis, clinically resembling RAS-mutant thyroid tumors." (PMID 36896180, 2023). "First, the comprehensive testing methods of the GC were able to detect the unique alterations characteristic of pediatric thyroid tumors, including gene fusions and DICER1 alterations." (PMID 35679040, 2022). "Most of our findings were supported by an exhaustive analysis of TCGA and human tumoral samples, allowing us to conclude that DICER1 downregulation in thyroid tumors is mediated, at least partly, through the impairment of its transcription." (PMID 33176626, 2021). "TCGA analysis revealed a significant positive correlation between CREB and DICER1 expression in human thyroid tumors." (PMID 33176626, 2021). "This agrees with data from the Human Protein Atlas, in which DICER1 protein levels are decreased in thyroid tumor samples." (PMID 33176626, 2021). "We found that PAX8 and NKX2-1 levels are significantly reduced in DICER1-silenced human thyroid tumor cells, whereas the opposite is seen in DICER1 overexpressing cells." (PMID 33176626, 2021). "The mutational status in the hot spot regions of DICER1, DROSHA, TARBP2, DGCR8 and the most commonly affected genes in thyroid tumors was investigated on both tumor and paired normal tissues." (PMID 30956758, 2019). "Systemic injection of an anti-miR-146b in mice with orthotopic thyroid tumors suppressed tumor growth and recovered DICER1 levels." (PMID 30967628, 2019). "The higher number of downregulated miRNAs relative to upregulated miRNAs in thyroid tumors suggests an important role of potential tumor-suppressive miRNAs in this cancer type, and are in line with the findings of DICER1 downregulation." (PMID 30967628, 2019). "Several mutations in the Ribonuclease III domain of DICER1 were previously reported in PTC and other types of cancer, but DICER1E1705Q mutation was first to be identified in thyroid tumor." (PMID 27494611, 2016). "First, we aimed to determine whether RET/PTC3 thyroid tumors exhibit downregulation of Dicer1 mRNA expression compared to WT thyroids, as observed in human PTC." (PMID 41002430, 2025). "The observed reduced weight of the RET/PTC3 Dicer1(−/−) thyroid tumors could result from increased cell death, potentially through apoptosis." (PMID 41002430, 2025). "In particular, several authors have documented the presence of somatic DICER1 variants in encapsulated thyroid tumors with macrofollicular architecture and lack of vascular invasion, typically occurring in young women, with an excellent prognosis." (PMID 40448797, 2025). "Indeed, Dicer1 mRNA levels were downregulated in thyroids from 4- and 8-month-old RET/PTC3 Dicer1(+/+) thyroid tumors compared to WT thyroids." (PMID 41002430, 2025). "Future investigations of dysregulated miRNAs in DICER1 and DGCR8 mutated tumors may provide important clues for thyroid tumor initiation and progression." (PMID 38252873, 2024).
thyroid tumor (continued). "Analysis of Dicer1 mRNA expression in normal tissues (n = 59), thyroid tumors (PTC, n = 505), and metastatic samples (n = 8), using data from The Cancer Genome Atlas (TCGA), revealed significant downregulation of Dicer1 mRNA in PTC and metastases compared with normal thyroid tissues." (PMID 39409030, 2024). "The discovery of two separate syndromes caused by mutations in genes controlling the maturation of micro-RNA (DICER1 and DGCR8) has been particularly interesting from a thyroid point of view, as these patients develop thyroid follicular nodular disease (TFND) and thyroid tumors." (PMID 38637342, 2024). "In contrast to many non-thyroidal tumors associated with DICER1 mutations, the pathology of hyperplastic nodules and DTC lacks specific histologic features that distinguish them from their non-DICER1 mutated counterparts." (PMID 38254836, 2024). "Examples of tumors apart from PPBthat may arise in a DICER1 kindred include ovarian Sertoli–Leydig celltumors, cystic nephromas, thyroid neoplasms and embryonal rhabdomyosarcoma,particularly affecting the cervix and the uterine corpus." (PMID 39601261, 2024). "Other more recent studies, not included in the COSMIC-derived dataset, have reported DICER1 mutations in thyroid neoplasms." (PMID 37867524, 2023). "E2F transcription factor binding sites were also found to be significantly overrepresented in the collection of upregulated genes based on TRANSFAC analysis, pointing to these transcription factors as important hubs in the cell-cycle regulation of DICER1-mut thyroid tumors." (PMID 36896180, 2023). "We previously reported low DICER1 mRNA levels in thyroid tumors." (PMID 33176626, 2021). "We also found a positive correlation between NKX2-1 and DICER1 expression in human thyroid tumors." (PMID 33176626, 2021). "Undifferentiated thyroid tumors lose their response to TSH and its downstream signaling, and this loss in the most undifferentiated tumors could explain, at least in part, the DICER1 downregulation observed in thyroid tumors." (PMID 33176626, 2021). "Notably, DICER1 expression in the primary thyroid tumor was higher after systemic anti-miR-146b treatment." (PMID 30967628, 2019). "Overall, these data strongly suggest an important role for DICER1 in thyroid tumor progression." (PMID 30967628, 2019). "Indeed, we observed increased γH2AX staining in RET/PTC3 Dicer1(−/−) thyroid tumors, which corresponded with the elevated TUNEL staining, supporting the hypothesis that cell death is triggered by the accumulation of DNA damage." (PMID 41002430, 2025). "However, in RET/PTC3 Dicer1(−/−) thyroid tumors, Bim mRNA expression remained slighly upregulated." (PMID 41002430, 2025). "However, DICER1 mutations are more prevalent in two conditions: The first is a follicular-patterned thyroid tumor in children (particularly if younger than 10 years old) where a follicular thyroid carcinoma could be the first manifestation of DICER1 syndrome." (PMID 38254836, 2024). "Another study linked hotspot DICER1 mutations to pediatric PTC (c.5125G>A p.D1709N, c.5428G>T p.D1801Y, c.5438A>G p.E1813G, c.5439G>C p.E1813D) with increased incidence in the patients that do not harbor MAPK classic alterations, suggesting a role for DICER1 mutation detection in thyroid tumors." (PMID 33218058, 2020). "Indeed, we confirmed low DICER1 mRNA levels in a panel of seven PTC thyroid tumors." (PMID 30967628, 2019). "On the other hand, the WT allele (478 bp) was present in the follicular cells from WT thyroids and RET/PTC3 Dicer1(+/−) and RET/PTC3 Dicer1(+/+) thyroid tumors, as expected, but also in RET/PTC3 Dicer1(−/−) thyroid tumors." (PMID 41002430, 2025). "Future studies employing dedicated mitochondrial functional assays will be crucial to assess the metabolic consequences of DICER1- and DGCR8-related miRNA biogenesis disruption in thyroid tumours." (PMID 41104964, 2025).
thyroid tumor (continued). "However, we found that thyroid tumors from 4-month-old and 8-month-old RET/PTC3 Dicer1(−/−) mice were significantly smaller than those from RET/PTC3 Dicer1(+/−) and RET/PTC3 Dicer1(+/+) mice, indicating that the complete loss of Dicer1 leads to a reduction in tumor size." (PMID 41002430, 2025). "A significant increase in the number of vimentin-positive cells was observed in thyroid tumors from 2-, 4- and 8-month-old RET/PTC3 Dicer1(+/+) mice compared to WT thyroids, which was expected given the tumoral context." (PMID 41002430, 2025). "While Ogg1 mRNA expression was not modified, we observed a downregulation of Gpx2 and Nqo1 mRNA expression in thyroid tumors from 2- and 8-month-old RET/PTC3 Dicer1(+/+) mice compared to WT thyroids, suggesting that redox homeostasis is unbalanced in RET/PTC3 tumors." (PMID 41002430, 2025). "The upregulation of Bim mRNA expression decreased over time, and by 8 months of age, Bim expression levels had returned to baseline in RET/PTC3 Dicer1(+/+) and RET/PTC3 Dicer1(+/−) thyroid tumors, reaching values comparable to those observed in the WT condition." (PMID 41002430, 2025). "However, Dicer1 exon 24 mRNA levels were markedly decreased in thyroid tumors from 2, 4- and 8-month-old RET/PTC3 Dicer1(−/−) tumors." (PMID 41002430, 2025). "This latter observation is in good agreement with the lack of correlation between CREM and DICER1 mRNA levels in human thyroid tumors." (PMID 33176626, 2021). "Similarly, Bim mRNA expression levels were upregulated in RET/PTC3 Dicer1(−/−) and RET/PTC3 Dicer1(+/−) thyroid tumors, showing no impact of Dicer1 inactivation." (PMID 41002430, 2025). "However, the precise role that DICER1 plays in thyroid tumor progression is not clear." (PMID 30967628, 2019). "Although thyroid tumors weights from RET/PTC3 Dicer1(+/+) and RET/PTC3 Dicer1(+/−) mice were not significantly different, RET/PTC3 Dicer1(−/−) tumors exhibited slightly slower growth curves and reduced tumor weight at 4 and 8 months of age." (PMID 41002430, 2025).
sarcoma (26 papers, 2015 to 2026). A usually aggressive malignant neoplasm of the soft tissue or bone. "Our clinical experiences highlight the potential of targeted therapeutics in the management of DICER1 sarcomas with known targetable mutations." (PMID 40634537, 2025). "There is currently no universally accepted systemic therapy approach for the treatment of patients with DICER1-associated sarcomas." (PMID 40634537, 2025). "As additional knowledge is gained regarding the molecular characterization of DICER1-associated sarcomas, an evaluation of the use of molecularly targeted therapies as precision-driven therapeutic options is necessary." (PMID 40634537, 2025). "Mutations in intracranial DICER1 mutant sarcomas were also mainly localized to the RNase IIIb domain (81%)." (PMID 40361440, 2025). "Recently, characteristic histopathology findings and distinct methylation signatures have been described in DICER1-associated sarcomas in variable anatomical locations and lend strong evidence that they constitute a distinct sarcoma entity." (PMID 40634537, 2025). "Given the limited knowledge, many patients with DICER1-associated sarcomas are treated on similar general soft tissue sarcoma regimens." (PMID 40634537, 2025). "The gaps in understanding the clinical presentation, diagnostic criteria, and treatment of Primary intracranial DICER1-mutant sarcoma (PIDMS) lead to poor patient outcomes globally." (PMID 41522384, 2025). "Here, we report on the clinical outcomes of two patients with metastatic DICER1-associated sarcomas who had transient responses to molecularly targeted therapies used in the relapsed setting." (PMID 40634537, 2025). "DICER1-associated sarcomas often demonstrate unique histopathologic features of variably cellular spindled cells accompanied by rhabdomyoblastic differentiation and occasional cartilaginous differentiation." (PMID 40634537, 2025). "Further studies are needed to understand the potential role of targeted therapies in this patient population, as there is not currently a uniformly accepted standard of care systemic treatment for patients with DICER1-associated sarcomas." (PMID 40634537, 2025). "DICER1 sarcoma (case 2) was originally diagnosed as MTT based on the loss of H3K27me3 expression on immunohistochemistry." (PMID 38178234, 2024). "Recent literature hints towards a distinct DICER-1 sarcoma entity characterized by specific mutational clusters." (PMID 38976022, 2024). "Mutations in DICER1 have been observed in various sarcomas, with a particular prevalence in the genitourinary tract." (PMID 38570882, 2024). "Recently, a comprehensive molecular and epigenetic study of DICER1-associated sarcomas has shown that some SLCTS with rhabdomyoblastic differentiation cluster close to DICER1-associated sarcomas." (PMID 38136408, 2023). "Among these entities, DICER1-associated sarcomas, sometimes presenting as a pelvic or adnexal mass, are composed of undifferentiated tumor cell proliferation, with atypia, and numerous mitoses." (PMID 38136408, 2023). "In two patients with intracranial tumors, the classifier changed the clinical suspicion of metastatic disease to a novel diagnostic tumor group (RMS-like sarcomas with DICER1 mutation)." (PMID 36380356, 2022). "Subsequent methylation analysis for sarcomas matched the tumor to a malignant spindle cell sarcoma with RMS-like features which commonly carry a DICER1-mutation (calibrated score: 0.99)." (PMID 36380356, 2022).
sarcoma (continued). "Apart from uterine sarcomas, DICER1 alterations have also been reported in other rare sarcoma entities, such as anaplastic sarcoma of the kidney and a recently described primary intracranial sarcoma with DICER1 mutation." (PMID 33846547, 2021). "DICER1-associated sarcomas commonly exhibit cooperating mutations involving RAS signaling pathways, but the efficacy of therapies that target these mutations is unknown." (PMID 40634537, 2025). "A growing number of studies have unveiled recurrent genetic alterations in DICER1-associated sarcomas, which may suggest putative targets for therapeutic interventions." (PMID 40634537, 2025). "Genomic alterations in RAS signaling pathways are frequently found in DICER1-associated sarcomas." (PMID 40634537, 2025). "Mutations in DICER1 (either somatic or germline) have been detected in a wide range of sarcomas." (PMID 38976022, 2024). "However, a review of 79 gynecological sarcomas has reported the presence of at least one DICER1 mutation, either somatic or germline." (PMID 38570882, 2024). "Moreover, immunohistochemistry was positive for stemness marker SALL4, which is typically associated with loss of H3K27me3 in DICER1 sarcomas." (PMID 38178234, 2024). "A wide variety of DICER1-associated sarcomas have been reported in the literature." (PMID 36983010, 2023). "However, an epigenetic overlap with extracranial sarcomas harboring DICER1 mutation remains undetermined." (PMID 36737790, 2023). "Moreover, considering the recent molecular data concerning DICER1-associated sarcomas, the latter diagnosis, as well as poorly differentiated SLCTS, must be considered in the case of a DICER1 variant identification in a “fibrosarcomatous-like” neoplasm." (PMID 38136408, 2023). "Furthermore, DICER1-associated sarcomas of various locations show a significant morphological overlap with other DICER1-associated neoplasms such as PPB and Sertoli–Leydig-cell tumors." (PMID 33846547, 2021). "Thus, it is possible that some DICER1-associated sarcomas could correspond or could develop from a poorly differentiated SLCT, expanding the plasticity of Sertoli cells in sex cord–stromal tumors of the ovary." (PMID 38136408, 2023). "In contrast to LGMT DICER1, DICER1-associated sarcomas may show a more aggressive clinical course." (PMID 36966138, 2023). "For example, distinguishing this entity from gliomas or other intra‐axial tumors with similar histologic appearance (including the immature morphology of the DICER1 mutant sarcoma with chondroid differentiation), can be difficult." (PMID 41473422, 2025). "In the sections below, we outline the clinical and genetic backgrounds of three intracranial DICER1-associated cancer types in pediatrics: ETMR, sarcomas, and pineoblastomas." (PMID 40361440, 2025). "The precise molecular differentiation plays a crucial therapeutic role, as DICER1 intracranial tumors′ treatment of choice is peripheral sarcomas adapted chemotherapy after surgery." (PMID 41473422, 2025). "Recent studies point towards a new distinct molecular subtype: DICER1-related sarcomas primarily located in the (female) genitourinary tract, that have some similarities to eRMS." (PMID 39847050, 2025). "Primary Intracranial DICER1-Mutant Sarcoma (PIDMS) is a rare brain tumor with limited data available on its clinical presentation, treatment, and prognosis." (PMID 41522384, 2025). "In summary, our analysis collates the current knowledge on the genetic basis of ETMR and DICER1 mutant intracranial sarcomas." (PMID 40361440, 2025).